ANGPTL2 (angiopoietin like 2)
Diseases named in the same sentence as ANGPTL2 in open-access papers (continued):
Sharing a sentence is not in itself a finding about the gene and the disease.
atherosclerosis (29 papers, 2013 to 2025). A disease characterized by the build-up of fatty material and calcium deposition in the arterial wall resulting in partial or complete occlusion of the arterial lumen. "Since ANGPTL2, 3, and 4 are associated with lipid metabolism and atherosclerosis, we examined the expression of ANGPTL2, 3, 4, and inflammatory cytokines in the EAT of patients with CAD and non-CAD by qRT-PCR." (PMID 35566578, 2022). "Recently, disruption of ANGPTL2 in apolipoprotein E-deficient mice (ApoE-/-/Angptl2-/-) was found to attenuate atherosclerosis progression by decreasing the number of macrophage infiltrating atheromatous plaques, thereby reducing vascular inflammation." (PMID 25889082, 2015). "Angiopoietin-like protein 2 (Angptl2) is a secreted glycoprotein that has been implicated in angiogenesis, inflammation and atherosclerosis as well as enhancing the survival of human hematopoietic stem cells." (PMID 25077060, 2014). "Angiopoietin-like proteins, including ANGPTL2, have also been analyzed as oncological biomarkers and therapeutic targets in tumor angiogenesis, and they are implicated in cardiovascular diseases, such as heart failure and atherosclerosis." (PMID 40278353, 2025). "The aim of this study was to investigate whether serum ANGPTL2 concentration is associated with atherosclerosis by measuring carotid intima-media thickness (IMT) in subjects with type 2 diabetes without previous history of cardiovascular diseases." (PMID 25889082, 2015). "In our current study, we investigated whether serum ANGPTL2 concentration was associated with the parameters of atherosclerosis in subjects with type 2 diabetes using carotid artery intima-media thickness (IMT), a non-invasive index of early atherosclerosis." (PMID 25889082, 2015). "Furthermore, it remains unclear about to what extent ANGPTL2 contributes to the development of atherosclerosis independently of conventional cardiovascular risk factors, especially in subjects with type 2 diabetes." (PMID 25889082, 2015). "ANGPTL2, an inflammatory mediator, has been shown to exacerbate vascular inflammation and atherosclerosis." (PMID 39040847, 2024). "In mice, overexpression of ANGPTL2 or exposure to recombinant ANGPTL2 promoted endothelial dysfunction and atherosclerosis." (PMID 38426206, 2024). "ANGPTL2 is a secreted protein, and its circulating levels increase with age and with chronic inflammatory diseases such as cancer, atherosclerosis, diabetes, and heart failure and with several age-related diseases." (PMID 37736764, 2023). "The importance of LILRB2 in human atherosclerosis is increasingly evident with reports linking the LILRB2 ligand ANGPTL2 to cardiovascular disease." (PMID 35321392, 2021). "There are also several lines of evidence supporting the participation of ANGPTL2 in atherosclerosis and heart failure." (PMID 34422408, 2021). "ANGPTL2 plays pivotal roles in various inflammatory diseases such as vascular inflammation, obesity, insulin resistance, and atherosclerosis." (PMID 34422408, 2021). "In pathological conditions, endothelial cells and infiltrated macrophages producing excess ANGPTL2 induced an inflammatory response by activating NF- κB signaling, which promoted endothelial dysfunction and atherosclerosis progression." (PMID 33256685, 2020). "In line with these previous findings, recent studies propose that plasma ANGPTL2 is a promising biomarker for inflammatory diseases such as various cancers, atherosclerosis, diabetes and heart failure." (PMID 27101308, 2016). "For instance, several experimental studies have suggested the biological relevance of ANGPTL2 as a regulator of atherosclerosis in rodents." (PMID 25889082, 2015). "Despite these limitations, our current study is meaningful in that we demonstrated the relationships between serum ANGPTL2 concentration and early subclinical atherosclerosis in humans, especially in subjects with type 2 diabetes." (PMID 25889082, 2015).
atherosclerosis (continued). "Thus, ANGPTL2 signaling has been reported to be important in the atherosclerosis process, angiogenesis, chronic inflammation, metabolic and lipid disorders and some types of cancer." (PMID 37189824, 2023). "Angiopoietin-like 2 promotes vascular inflammation, endothelial dysfunction, and atherosclerosis." (PMID 34220553, 2021). "This suggests that ANGPTL2 from these cells may contribute to endothelial dysfunction and progression of atherosclerosis." (PMID 31743976, 2019). "Angiopoietin-like 2 protein (ANGPTL2), a pro-inflammatory circulating protein related to chronic inflammatory disease including diabetes and atherosclerosis, was recently identified as another valuable predictor of cardiovascular events and death in diabetic patients." (PMID 29879997, 2018). "Serum ANGPTL2 concentration was significantly and positively associated with carotid atherosclerosis in patients with type 2 diabetes, suggesting that ANGPTL2 may be important in the atherosclerosis in humans." (PMID 25889082, 2015). "Considering the reported harmful effects of ANGPTL2 on vascular inflammation in rodents, our current findings provide further evidence that this protein may play a key role in atherosclerosis in humans." (PMID 25889082, 2015). "Although these findings support the concept that ANGPTL2 is more likely to be involved in the regulation of vascular function, more specifically in atherosclerosis in rodents, few studies have examined the relevance of circulating ANGPTL2 levels to subclinical atherosclerosis in humans." (PMID 25889082, 2015). "Our current evidence may suggest the independent involvement of ANGPTL2 in the pathogenesis of early subclinical atherosclerosis in humans, especially in subjects with type 2 diabetes." (PMID 25889082, 2015). "This further supports the recently proposed notion that ANGPTL2 may be an important factor in the pathogenesis of atherosclerosis in humans, similarly to its possible role in the regulation of vascular function in rodents." (PMID 25889082, 2015). "Moreover, since vascular injury along with vascular inflammation are considered an early manifestation of arteriosclerosis, serum ANGPTL2 levels might be involved in the arteriosclerotic process and could act as a new biomarker of atherosclerosis." (PMID 37189824, 2023). "ANGPTL2 and p21 expression are tightly associated in non-atherosclerotic human arteries, which further suggests that accumulation of arterial senescence precedes age-related atherosclerosis." (PMID 31186381, 2019). "Although these previous data support the hypothesis that serum ANGPTL2 is strongly related to atherosclerosis in humans, little is known whether this role of ANGPTL2 applies in purely type 2 diabetes cases and/or in subject with early stage atherosclerosis." (PMID 25889082, 2015). "ANGPTL2 methylation has not been studied in CVD, despite considerable evidence now showing that DNA methylation is associated with inflammation and atherosclerosis." (PMID 27101308, 2016). "That is, the upregulated circulating ANGPTL2 levels in the HF patients could not simply be explained by the presence of advanced atherosclerosis." (PMID 26397985, 2015).
Insulin resistance (27 papers, 2013 to 2026). Increased resistance towards insulin, that is, diminished effectiveness of insulin in reducing blood glucose levels. "ANGPTL2 causes insulin resistance (IR) in adipose tissue and is associated with HOMA-IR in obese women." (PMID 34422408, 2021). "Parallel measurement of ANGPTL2 mRNA in VAT and SAT and serum ANGPTL2 revealed not only their inter-relationships, but also their close associations with adiposity, inflammation, and insulin resistance." (PMID 30228336, 2018). "Adipose tissue ANGPTL2 mRNA and serum ANGPTL2 levels showed strong associations with metabolic parameters associated with insulin resistance." (PMID 30228336, 2018). "Understanding the underlying mechanisms by which ANGPTL2 induces adipose tissue inflammation would provide new insight into therapeutic strategies for cardiometabolic diseases caused by insulin resistance." (PMID 26132105, 2015). "A deficiency of ANGPTL2 improves adipose tissue inflammation and insulin resistance in diet-induced obese mice, whereas its overexpression in adipose tissue promotes inflammation as well as insulin resistance in mice." (PMID 24733068, 2014). "As reviewed previously, ANGPTL2 primarily derived from visceral fat is positively associated with inflammation and insulin resistance, while ANGPTL6 expressed in the liver is found to counteract obesity and insulin resistance by suppressing gluconeogenesis and enhancing energy expenditure." (PMID 35693558, 2022). "Existing studies suggest that ANGPTL2 expression and circulation are augmented in high-fat diet conditions and associated with local inflammation, an increase in macrophage accumulation, endothelial injury, adipose tissue-specific pro-inflammatory M1 polarization, and systemic insulin resistance." (PMID 40427505, 2025). "While associations of adipose tissue ANGPTL2 mRNA with metabolic parameters disappeared after adjusting for BMI, serum ANGPTL2 strongly correlated with the degree of hyperglycemia, hypertriglyceridemia, insulin resistance, and visceral obesity after adjustment for BMI." (PMID 30228336, 2018). "Extended NF-ƘB signaling activation by ANGPTL2 affects pancreatic and hepatic functioning and accounts for the development of T2D and insulin resistance." (PMID 40427505, 2025). "In obese mice, increased ANGPTL2 levels resulted in persistent inflammation and restructuring of adipose tissue, ultimately leading to systemic insulin resistance." (PMID 39139157, 2024). "What's noteworthy is that ANGPTL2 also exerts pivotal roles in angiogenesis, androgen biosynthesis, adipocyte function, and insulin resistance." (PMID 35747760, 2022). "Treatment of diabetic mice with recombinant ANGPTL2 amplified insulin resistance, while genetic deletion of this protein improved adiposity and systemic insulin resistance." (PMID 34422408, 2021). "In obese women with insulin resistance, ANGPTL2 production by adipocytes was shown to upregulate proinflammatory cytokine production in macrophages, in turn increasing adipose tissue inflammation, systemic insulin resistance and hyperinsulinaemia." (PMID 33392801, 2021). "Angiopoietin-like protein 2 (ANGPTL2) is one of the adipocyte-derived inflammatory factors which connects obesity to insulin resistance." (PMID 34422408, 2021). "In obese mice, a decrease in ANGPTL2 attenuated the inflammatory responses and improved insulin resistance." (PMID 33133214, 2020). "On the other hands, Tabata M and his colleagues reported that in mice with defection in ANGPTL2, adipose tissue inflammation and insulin resistance improved." (PMID 29932432, 2018). "Through studies employing obese or diabetic animals, ANGPTL2 has been shown to play an important role in adipose tissue inflammation and insulin resistance." (PMID 30228336, 2018).
Insulin resistance (continued). "ANGPTL2 mRNA in adipose tissues, especially in VAT, showed significant associations with metabolic parameters influenced by inflammation, dyslipidemia, and insulin resistance; however, the significant correlations were abolished after adjustment for BMI." (PMID 30228336, 2018). "ANGPTL2 has an important effect on angiogenesis, androgen biosynthesis, adipocyte function, and insulin resistance." (PMID 29932432, 2018). "A more recent study, however, reported opposing effects that four week of recombinant ANGPTL2 treatment improved insulin resistance in db/db mice." (PMID 26132105, 2015). "In conclusion, we propose that ANGPTL2 promotes adipose tissue inflammation as gauged by accumulation and activation of macrophages and T lymphocytes, leading to systemic insulin resistance." (PMID 26132105, 2015). "In the animal model, ANGPTL2 deletion ameliorated both the adipose tissue inflammation and systemic insulin resistance in diet-induced obese mice." (PMID 26397985, 2015). "The same article also demonstrated that adipose tissue-specific Angptl2 overexpression induced fat inflammation and insulin resistance." (PMID 26132105, 2015). "ANGPTL2 deletion has also been shown to ameliorate adipose tissue inflammation and systemic insulin resistance in diet-induced obese mice." (PMID 24478758, 2014). "Expression of ANGPTL2 in adipose tissue and circulating levels of ANGPTL2 are higher in diet-induced obese mice than in control mice, and circulating levels of ANGPTL2 are closely related to adiposity, insulin resistance, and inflammation in mice." (PMID 24733068, 2014). "Circulating levels of ANGPTL2 correlate with inflammation, adiposity, and insulin resistance in both mice and humans." (PMID 24478758, 2014). "In summary, ANGPTL2 can be considered a key mediator that links obesity to systemic insulin resistance and plays a pivotal role in the atherosclerotic process and in the development of diabetes." (PMID 24478758, 2014). "ANGPTL2 was recently identified as an adipocyte-derived inflammatory mediator that promotes inflammation and insulin resistance." (PMID 24733068, 2014). "ANGPTL2 is a newly identified adipokine (i.e. it falls under the newly identified ANGPTL family), and it has been linked to various metabolic disorders such as insulin resistance, obesity, and diabetes." (PMID 39139157, 2024). "Among them, Lcn2 and Angptl2 have been reported to promote inflammation and insulin resistance." (PMID 35655797, 2022). "Conversely, increased ANGPTL2 promoted inflammation in adipose tissue and insulin resistance." (PMID 33133214, 2020). "Conversely, overexpression of ANGPTL2 in adipose tissue causes local inflammation and systemic insulin resistance in non-obese mice." (PMID 30228336, 2018). "We speculate that this persistent stimulation of ANGPTL2 protein induced chronic inflammation and led worse insulin resistance." (PMID 26132105, 2015). "Likewise, ANGPTL2 plays pivotal roles in various inflammatory diseases such as vascular inflammation, obesity, insulin resistance, cancer rheumatoid arthritis, and atherosclerosis." (PMID 26132105, 2015). "Conversely, ANGPTL2 overexpression in adipose tissue also caused local inflammation and systemic insulin resistance in non-obese mice." (PMID 26397985, 2015). "Given the significant correlation between ANGPTL2 levels and insulin resistance and the recent evidence of its pro-oxidant effect, ANGPTL2 could also be useful as a biomarker of endothelial dysfunction." (PMID 24478758, 2014). "In addition, co-culture of adipocytes and macrophages suggested that ANGPTL2 excessively produced by adipocytes, may contribute inflammation and remodeling in obese adipose tissues, thereby promoting insulin resistance." (PMID 30228336, 2018).
Insulin resistance (continued). "Severity of insulin resistance should vary depending on the age of db/db mice, which may in turn affect the function of ANGPTL2 because adipocytes may expose more pro-inflammatory environment and produce more adipokines, leading to more insulin resistant state under more obese condition." (PMID 26132105, 2015). "Thus, the functional role of ANGPTL2 on insulin resistance remains obscure." (PMID 26132105, 2015). "Instead, ANGPTL2 may indirectly induce insulin resistance by enhancing inflammation." (PMID 26132105, 2015). "Adipokines that stimulate insulin resistance include MCP‐1, RBP‐4, progranulin, chemerin, and ANGPTL2." (PMID 32440558, 2020). "Thus, the function of ANGPTL2 on insulin resistance and type 2 diabetes remains unclear." (PMID 26132105, 2015). "In addition, it suggests that ANGPTL2 produced by adipocytes up-regulates MMP9 and proinflammatory cytokine production in macrophages, thereby promoting adipose tissue inflammation, remodeling, and systemic insulin resistance." (PMID 30228336, 2018). "Therefore, we concluded that increased human ANGPTL2 levels induced adipose tissue inflammation and led to insulin resistance, not by affecting the circadian gene expression." (PMID 26132105, 2015). "Therefore, the relationship between circulating ANGPTL2 levels, visceral fat, and insulin resistance index could not be analyzed." (PMID 26397985, 2015).
diabetes (24 papers, 2013 to 2025). "In the Hisayama study, raised serum ANGPTL2 levels were positively associated with the development of type 2 diabetes mellitus in community-dwelling Japanese subjects." (PMID 37189824, 2023). "Studies have shown that ANGPTL2 increases in HF, and higher ANGPTL2 levels will increase the risk of HF and ANGPTL2 is an independent risk factor for diabetes development." (PMID 36465455, 2022). "ANGPTL2 has been connected to major adverse cardiovascular events in patients with diabetes and has been introduced as a novel risk factor in developing CVD in the general population." (PMID 34422408, 2021). "After adjusting for age, sex, HbA1C and duration of diabetes, ANGPTL2 was found to be independently associated with the presence of DFUs." (PMID 33256685, 2020). "ANGPTL2 is a pro-inflammatory protein that is associated with chronic inflammatory diseases including diabetes, atherosclerosis and cancer that is extensively expressed in visceral adipose tissue." (PMID 29932432, 2018). "In subjects with diabetes, serum ANGPTL2 levels were associated with carotid intima-media thickness." (PMID 26397985, 2015). "In addition, ANGPTL2 is established as a pro-inflammatory protein associated with states of chronic inflammation, such as diabetes, atherosclerosis, and cancer, and is further widely expressed in visceral adipose tissues." (PMID 35747760, 2022). "Circulating angiopoietin-like 2 (ANGPTL2) protein levels are known to be significantly increased in numerous chronic inflammatory diseases and are associated with the diagnosis and/or prognosis of cardiovascular diseases, diabetes, chronic kidney disease, and various types of cancers." (PMID 33256685, 2020). "Two decades of research show that elevated circulating levels of pro-inflammatory and pro-oxidative angiopoietin like-2 (ANGPTL2) are independently associated with a risk of coronary artery disease, stroke, diabetes or kidney disease." (PMID 38426206, 2024). "Binary logistic regression analysis demonstrated ANGPTL2 was an independent risk factor for diabetic foot after adjusting for age, gender, HA1C, and duration of diabetes." (PMID 33256685, 2020). "Expression of transcription factors (ANGPTL2, HP, LEP, SAA1, SAA2), genes related to inflammation (SAA1, LEP), diabetes (IGFBP5) and cancer risk (SAA2) were also elevated upon exposure to 5 nM PhIP.." (PMID 27547236, 2016). "This study aimed to explore the role of ANGPTL2 in adipose tissue inflammation and macrophage activation in a mouse model of diabetes." (PMID 26132105, 2015). "This study suggests that β-receptor activation helps to maintain the metabolic profile of MHO individuals and prevent type 2 diabetes mellitus (T2DM) by decreasing serum ANGPTL2 levels." (PMID 23837045, 2013). "Various clinical studies have revealed that the ANGPTL2 level significantly increases in a variety of chronic inflammatory diseases and is related to the diagnosis and prognosis of chronic kidney disease, diabetes, cardiovascular diseases, and a variety of cancers." (PMID 35747760, 2022). "In a recent study conducted in a general community-dwelling Japanese population, elevated serum ANGPTL2 levels were positively associated with the development of type 2 diabetes mellitus independent of other risk factors including C-reactive protein (CRP) levels." (PMID 24478758, 2014). "The patients with diabetes had a significantly higher ANGPTL2 levels than those without diabetes (4.65ng/mL [3.64–5.86 ng/mL] vs. 3.7 ng/mL [2.93–4.96 ng/mL], P = 0.0002)." (PMID 26397985, 2015). "Moreover, adipocyte ANGPTL2 mRNA was noticeably higher in obese patients with or without diabetes than in normal weight subjects." (PMID 30228336, 2018).